RNU1-23P (RNA, U1 small nuclear 23, pseudogene)
Gene: Small nuclear RNA gene on chromosome 20 (24,237,255 to 24,237,398, forward strand). Ensembl gene ENSG00000200231.
Homologues: Orthologues: chimpanzee U1 (99% identical), macaque U1 (92% identical), rat U1 (60% identical), mouse Gm23895 (59% identical), rabbit U1 (44% identical). Paralogues in human: RNU1-1 (81% identical), RNU1-19P (81% identical), RNU1-2 (81% identical), RNU1-27P (81% identical), RNU1-28P (81% identical), RNU1-3 (81% identical), RNU1-4 (81% identical), RNVU1-18 (81% identical), RNVU1-28 (81% identical), RNVU1-29 (81% identical), U1 (81% identical), RNU1-138P (80% identical), and 133 more.